TMEM270 (transmembrane protein 270)
Synonyms: WBSCR28; MGC26719
Tractability: Antibody: UniProt predicts a signal peptide or a membrane-spanning region.
Gene: Protein-coding gene on chromosome 7 (73,861,159 to 73,865,890, forward strand). Ensembl gene ENSG00000175877.
Subcellular location: Membrane
Subcellular location (Human Protein Atlas): Vesicles
Gene Ontology:
Cellular component: membrane
Genetic constraint (gnomAD): Loss-of-function variants: 30 observed, 29.23 expected, observed/expected ratio (o/e) 1.03, 90% interval 0.77 to 1.39. The upper end of that interval is the gene's LOEUF score, 1.39, which puts it in group 5 of 6, group 1 being the genes least tolerant of losing a copy. Missense variants: 313 observed, 311.16 expected, observed/expected ratio (o/e) 1.01, 90% interval 0.92 to 1.11. Synonymous variants: 135 observed, 142.5 expected, observed/expected ratio (o/e) 0.95, 90% interval 0.82 to 1.09.
Homologues: Orthologues: chimpanzee TMEM270 (98% identical), macaque TMEM270 (92% identical), pig TMEM270 (65% identical), dog TMEM270 (63% identical), mouse Tmem270 (58% identical), rat Tmem270 (53% identical).